PRDM14 (PR/SET domain 14)
Diseases named in the same sentence as PRDM14 in open-access papers (continued):
Sharing a sentence is not in itself a finding about the gene and the disease.
tumor (continued). "Hence, the role of PRDM14 in tumor development is enigmatic and requires further research." (PMID 33291744, 2020). "PRDM14 bears a single PR domain and six tandemly repeated zinc fingers, which is involved in the process of the deacetylation and methylation of the histone, and is involved in the formation of tumor trough the change level of methylation in the promoter region." (PMID 26903163, 2016). "Correlation analysis showed that the methylation of the PRDM14, CACNA1E, CCDC181, and GCM2 genes correlated with tumor size." (PMID 37628841, 2023). "The level of methylation in four genes—PRDM14, CACNA1E, CCDC181, and GCM2—correlated with tumor size." (PMID 37628841, 2023). "For urine supernatant, there was a significant correlation between methylation levels of MAL, PHACTR3, PRDM14, SST and ZIC1 and the matched tumor tissues." (PMID 32252299, 2020). "In full void, methylation levels of GHSR, miR-129, PRDM14, SST and ZIC1 were significantly correlated to the matched tumor tissues." (PMID 32252299, 2020). "The correlation analysis in our study showed that LumB- is characterized by the methylation of two genes—PRDM14 and CACNA1E—which could be considered a potential prognostic marker of tumor progression." (PMID 37628841, 2023). "Using the methylation-specific digital karyotyping (MSDK) method, they found the transcriptional regulator PR/SET domain 14 (PRDM14) and transcription factor homeobox D4 (HOXD4) genes to be exclusively methylated in tumour epithelial cells and NFs respectively." (PMID 33066013, 2020). "We found expression of pluripotency factors OCT3/4, LIN28 and NANOG in the TCam-2-ΔSOX2/FOXA2 tumor tissues, but not of PRDM14, which is strongly upregulated in TCam-2 cells, which were reprogrammed to an EC-like cell fate." (PMID 31130628, 2019). "Interestingly, PRDM14 was also overexpressed in PDAC adjacent tissues, which were histologically non‐neoplasmic areas around the tumor, implying PRDM14 overexpression occurs at tumor origin and contributes to tumorigenesis." (PMID 30338223, 2018). "The chance that a retrovirus would integrate in such a manner as to allow expression of Prdm14 directly from the LTR elements is unlikely without this event contributing to tumor formation." (PMID 19043588, 2008).
PRDM14 also shares sentences with these, for which no sentence is quoted: ovarian carcinoma (2 papers); prostate carcinoma (2); adenocarcinoma (1); Alzheimer disease (1); autism (1); autism spectrum disorder (1); cardiomyopathy (1); diffuse large B-cell lymphoma (1); Fanconi anemia (1); Fibroadenoma (1); gastric cancer (1); head and neck squamous cell carcinoma (1); Hyperglycemia (1); Intellectual disability (1); invasive breast carcinoma (1); lung adenocarcinoma (1); lung squamous cell carcinoma (1); mammary adenocarcinomas (1); mesomelia-synostoses syndrome (1); pulpitis (1); renal carcinoma (1); teratoma (1); testicular tumors (1); tubulovillous adenoma (1).